ZNF516-DT (ZNF516 divergent transcript)
Synonyms: C18orf65
Gene: Long non-coding RNA gene on chromosome 18 (76,495,521 to 76,498,088, forward strand). Ensembl gene ENSG00000275763.
Diseases named in the same sentence as ZNF516-DT in open-access papers:
ZNF516-DT is named in the same sentence as 2 diseases in open-access papers, as found by Europe PMC text mining. Sharing a sentence is not in itself a finding about the gene and the disease.
ZNF516-DT shares sentences with these, for which no sentence is quoted: cleft lip (1 paper); cleft palate (1).